Y_RNA (Y RNA )
Gene: Miscellaneous RNA gene on chromosome 9 (21,160,235 to 21,160,336, reverse strand). Ensembl gene ENSG00000199635.
Homologues: Orthologues: chimpanzee Y_RNA (99% identical), guinea pig Y_RNA (91% identical). Paralogues in human: RNY3 (93% identical), Y_RNA (92% identical), RNY3P1 (91% identical), Y_RNA (91% identical), Y_RNA (90% identical), Y_RNA (89% identical), Y_RNA (88% identical), Y_RNA (87% identical), RNY3P11 (86% identical), RNY3P9 (86% identical), Y_RNA (86% identical), Y_RNA (85% identical), and 98 more.